PPARG (peroxisome proliferator activated receptor gamma)
Diseases named in the same sentence as PPARG in open-access papers (continued):
Sharing a sentence is not in itself a finding about the gene and the disease.
sarcoidosis (17 papers, 2007 to 2025). Sarcoidosis is a multisystemic disorder of unknown cause characterized by the formation of immune granulomas in involved organs. "Macrophage-specific peroxisome-proliferator-activated receptor gamma (PPARγ) knock out (KO) mice were studied along with wild-type mice because our previous report indicated PPARγ deficiency in sarcoidosis alveolar macrophages." (PMID 32405439, 2020). "As detailed above (see AM section) in sarcoidosis, the deficient PPARγ activity in AMs attracts more T cells and myeloid cells into the inflammatory milieu." (PMID 32722050, 2020). "In sarcoidosis, PPARγ activity is deficient in AMs, leading to an increase in the production of TNFα, IL-12, and MMPs, which cause lung damage and fibrosis and induction of T-cell chemotaxis." (PMID 32722050, 2020). "Alveolar macrophages of healthy individuals constitutively express PPARγ but PPARγ is deficient in alveolar macrophages from patients with severe sarcoidosis, suggesting that this factor represents an important regulator of inflammation." (PMID 23343389, 2013). "The transcription factor, peroxisome proliferator-activated receptor gamma (PPARγ) is deficient in sarcoidosis alveolar macrophages compared to healthy controls, while the pro-inflammatory regulator, nuclear factor kappa B (NF-κB), is activated." (PMID 24322444, 2013). "Because PPARγ deficiency is reported in sarcoidosis, we hypothesized that combined instillation of ESAT-6 and MWCNT might elicit immunological changes in macrophage-specific PPARγ-deficient (KO) mice that could resemble those reported in sarcoidosis." (PMID 32405439, 2020). "Moreover, PPARγ antagonist treatment of wild-type mice elevated T cell mediator production suggesting that persistent PPARγ deficiency such as noted in sarcoidosis alveolar macrophages may help to maintain an elevated Th1 cell profile." (PMID 32405439, 2020). "Mice receiving rosiglitazone had lower MWCNT-induced pulmonary granulomas in association with a reduced pro-inflammatory response, and sustained ABCG1 expression in macrophages, supporting the concept that PPARγ deficiency could play a role in sarcoidosis pathogenesis." (PMID 32751786, 2020). "A primary example of this approach was to study mice with a myeloid-specific knock-out of the lipid-regulated transcription factor, peroxisome proliferator-activated receptor gamma (PPARγ) which is strikingly depressed in sarcoidosis." (PMID 33918196, 2021). "Results were similar to findings in sarcoidosis: Twist1 protein was elevated in both wild-type and PPARγ KO alveolar macrophages after MWCNT instillation." (PMID 25525507, 2014). "Results from wild-type mice proved to be virtually identical to those we observed in sarcoidosis, with alveolar macrophages showing significantly depressed PPARγ activity and expression." (PMID 25525507, 2014). "PPARγ is constitutively expressed in alveolar macrophages from healthy individuals but is depressed in alveolar macrophages of patients with sarcoidosis, a prototypical granulomatous disease." (PMID 23343389, 2013). "PPARγ expression is dysregulated in patients with cystic fibrosis, sarcoidosis, COPD, and acute lung injury." (PMID 22778711, 2012). "Consistent with this idea, PPARγ markedly enhances phagocytosis in alveolar macrophages (reviewed in Croasdell) which intrinsically express high levels of PPARγ in healthy controls compared to patients with sarcoidosis." (PMID 32405439, 2020). "PPARγ was reduced in BAL lysates and nuclear PPARγ content in macrophages, suggesting that PPARγ could be an important negative regulator of inflammation in macrophages in sarcoidosis." (PMID 32751786, 2020). "Reduced PPARγ expression was demonstrated in lung fibroblasts from patients with SSc and in alveolar macrophages of patients with sarcoidosis and pulmonary alveolar proteinosis, suggesting that insufficient PPARγ activity may contribute to ongoing dysregulated inflammation and fibrosis." (PMID 26064084, 2015).
sarcoidosis (continued). "Thus, PPARα or PPARγ could be potential therapeutic targets in sarcoidosis." (PMID 25969669, 2015). "Findings suggest that Twist1 represents a PPARγ-sensitive alveolar macrophage M1 biomarker which is induced by inflammatory granulomatous disease in the MWCNT model and in human sarcoidosis." (PMID 24322444, 2013). "Overall, the evidence for elevated CCL2 in human sarcoidosis and in MWCNT-instilled wild-type and PPARγ KO mice suggests that this chemokine is an important element of inflammatory pulmonary granuloma formation." (PMID 23343389, 2013). "Of great interest, PLCL1, PPARG, CD19 have been involved in sarcoidosis through functional studies." (PMID 41466414, 2025). "Additionally, the miRNet tool showed three transcription factors (PPARG, NFKB1, and RELA) exhibited the highest levels of interaction with the common DEGs shared between sarcoidosis and LC." (PMID 40797277, 2025). "An explanation for this difference could be clinical differences in the study populations, since PPARγ gene expression in BAL cells seems only to be reduced in patients with severe and treatment requiring sarcoidosis." (PMID 25969669, 2015). "Our results suggest that the reduced expression of PPARα and PPARγ contribute to the persistent T-cell driven immunoresponse noted in non-resolving sarcoidosis, common in non-LS patients." (PMID 25969669, 2015). "In contrast to a previous finding we could not verify that PPARγ expression is reduced in whole BAL cells or AM from patients with sarcoidosis." (PMID 25969669, 2015). "The lower protein expression of PPARα and PPARγ could contribute to the persistent T-cell driven inflammation noted especially in non-resolving sarcoidosis, common in non-LS patients." (PMID 25969669, 2015).
schizophrenia (17 papers, 2013 to 2025). A major psychotic disorder characterized by abnormalities in the perception or expression of reality. "SYN2 has been previously linked with bipolar disorder and in GWAS with schizophrenia, whereas PPARG has also been linked to bipolar disorder and schizophrenia in other research." (PMID 32381021, 2020). "In schizophrenia, the expression of PPARγ could be increased while PPARα is downregulated, suggesting a metabolic-inflammatory imbalance in its pathogenesis." (PMID 35269952, 2022). "PPARγ agonists, which influence the WNT/β-catenin pathway and inflammatory processes, represent a potential therapeutic strategy, although more research is required to validate their efficacy and mechanism of action in the context of schizophrenia." (PMID 38673018, 2024). "In schizophrenia, the WNT/β-catenin pathway and the expression of PPARα act in a positive interplay, which in turn leads to this complex negatively interacting with the expression of PPARγ." (PMID 35269952, 2022). "According to various studies showing the ability of PPARγ agonists to induce the expression of BDNF, it is possible to propose a possible effect of drugs, such as RSG, in improving cognitive symptoms typical of schizophrenia." (PMID 31614739, 2019). "The core identified targets of aripiprazole include MAPK3 (mitogen-activated protein kinase 3), PPARG (peroxisome proliferator-activated receptor gamma), the D2 receptor, and ESR1 (estrogen receptor 1), providing new insights into the mechanisms of this drug in schizophrenia treatment." (PMID 40572510, 2025). "However, stimulating PPARγ would not be the expected therapeutic solution in schizophrenia because of its observed stimulation in schizophrenia." (PMID 35269952, 2022).
endometrial cancer (16 papers, 2006 to 2025). Primary or metastatic malignant neoplasm involving the endometrium (mucous membrane that lines the endometrial cavity). "From the studied PPARγ gene polymorphisms, the H449H variant seems to be overrepresented in women suffering from endometrial carcinoma." (PMID 37298140, 2023). "In this study we also demonstrated absence of mutation within the coding region of the hPPARα gene in the cell lines tested, as it is known that up to 15% of endometrial cancers harbour variants of PPARγ." (PMID 16569247, 2006). "Additionally, PPARγ expression levels were significantly associated with estrogen receptor α expression levels, alongside endometrial cancer pathological grade and clinical stage." (PMID 37298140, 2023). "In the Ishikawa and HEC-1A endometrial cancer cell lines, both the PPARα ligand fenofibrate and the PPARγ agonist ciglitazone impressively induced apoptosis and inhibited cellular proliferation." (PMID 37298140, 2023). "The PPARα and PPARβ/δ isoforms seemed to be upregulated, whereas PPARγ levels were reported to be significantly lower in endometrial cancer cells." (PMID 37298140, 2023). "The intersection between TZD administration, PPARG expression, and endometrial cancer development deserves additional study." (PMID 32894083, 2020). "Immunoreactivity of PPARγ was significantly lower in endometrial carcinoma tissue than in normal endometrial tissue (P<0.001)." (PMID 33197888, 2020). "The inhibition of cell proliferation in endometrial cancer cells was reduced using PPARγ antagonist, GW9662." (PMID 24667764, 2014). "It is suggested that telmisartan has anticancer effect through PPARγ dependent pathway in endometrial cancer cells." (PMID 24667764, 2014). "The nuclear hormone receptor peroxisome proliferator-activated receptor-gamma (PPARγ) and its ligands induce apoptosis in several types of cancers, including endometrial cancer." (PMID 24667764, 2014). "Positive PPAR (-α, -β, -γ) immunohistochemical staining was detected in normal endometrial mucosa (for PPAR α: 57%, PPAR β: 55%, and PPARγ: 61%) as well as in endometrial cancers (for PPARα: 78%; PPARβ: 77%; PPARγ: 84%)." (PMID 22448166, 2012). "In summary, we provide evidence for altered expression of different PPAR isoforms in endometrial cancer cells, namely, greater expression of PPARα and PPARβ, with concomitant reduction of PPARγ in EC." (PMID 22448166, 2012). "We found reduced immunohistochemical PPARγ expression in EC, which is consistent with other reports showing rather moderate immunoreactivity of PPARγ expression in endometrial carcinoma cells." (PMID 22448166, 2012). "Conversely, the inhibition of ERα expression may result in the upregulation of peroxisome proliferator-activated receptor gamma (PPARγ), which, in turn, may lead to the inhibition of proliferation in endometrial cancer cells." (PMID 39194700, 2024). "PPARγ is undoubtedly the most studied PPAR isoform in endometrial cancer." (PMID 37298140, 2023). "Most importantly, copy number variations and nucleotide mutations in the exon regions of PPARs differentially influenced endometrial cancer prognosis and overall survival, while a PPARγ/estrogen-related receptor-α ratio ≤1.86 constituted an independent risk factor for endometrial carcinogenesis." (PMID 37298140, 2023). "However, the relationship between ERRα and PPARγ in the development of endometrial cancer (EC) is still unclear." (PMID 33197888, 2020). "In opposite, PPARγ protein expression was lower in endometrial cancer cells." (PMID 22448166, 2012). "Most research groups reported PPARγ downregulation, but PGC-1α upregulation, in endometrial cancer." (PMID 37298140, 2023). "A similar situation is seen in endometrium carcinoma, where benign lesions show strong PPARγ immunoreactivity but malignant lesions low to absent PPARγ expression." (PMID 25866814, 2015).
endometrial cancer (continued). "Notably, the PPARγ agonist 15-Deoxy-Δ12,14-prostaglandin J2 successfully inhibited cancer cell proliferation and promoted p21 mRNA expression in the Ishikawa, Sawano, and RL95-2 endometrial carcinoma cell lines." (PMID 37298140, 2023). "Furthermore, investigations into specific compounds, such as kaempferol and quercetin, suggest their role in modulating PPARG expression and interacting with AKT1, pointing towards potential treatment avenues for endometrial cancer and nonsegmental vitiligo." (PMID 38505269, 2024).
scleroderma (16 papers, 2010 to 2025). Scleroderma is a rare autoimmune connective tissue disorder characterized by abnormal hardening of the skin and, sometimes, other organs. "In contrast, rosiglitazone (Rosi), a PPARγ agonist, abrogates bleomycin-induced scleroderma and blocks profibrotic responses." (PMID 35324426, 2022). "Other nonthiazolidinic PPARγ ligands, AjA and CDDO, also reduced collagen neosynthesis by scleroderma fibroblasts in vitro, an action that was reversed completely by cotreatment with a selective PPARγ antagonist." (PMID 26064084, 2015). "PPARγ expression is reduced in dermal fibroblasts isolated from fibrotic areas of scleroderma patients; PPARγ agonists suppress the persistent fibrotic phenotype of this cell type." (PMID 22502865, 2012). "Also, Rosiglitazone-mediated PPARγ activation inhibits Egr-1 generation, leading to suppression of bleomycin-induced scleroderma and profibrotic responses." (PMID 33717177, 2021). "Moreover, functional studies showed that PPARG agonist attenuated dermal fibrosis in mice with bleomycin-induced scleroderma." (PMID 24401602, 2014). "Peroxisome proliferator activated receptor gamma (PPAR-γ), a master regulator of adipogenesis, inhibits profibrotic responses induced by transforming growth factor-ß (TGF-β), and its expression is impaired in scleroderma." (PMID 23092446, 2012). "Indeed, another PPARγ and CB2 co-activator (and CB1 antagonist), namely “VCE-004.3” (a semi-synthetic CBD quinol derivative) was also found to alleviate bleomycin-induced scleroderma as well as exerting potent anti-fibrotic effects via activating PPARγ and CB2." (PMID 30845666, 2019). "Although the relationship of EGR-1 and PPARγ in the kidney has not been investigated yet, the PPARγ agonist rosiglitazone decreased skin fibrosis and EGR-1 levels in a mouse model of scleroderma." (PMID 31277592, 2019). "Finally, analysis of human scleroderma skin tissues revealed a negative correlation between the expression of AP‐, ECM‐, and TGFβ pathway‐related genes and PPARG." (PMID 39072821, 2025).
hematoma (15 papers, 2015 to 2025). A hematoma is a collection of blood from a vascular structure into an extravascular space. "Accordingly, we demonstrate that APN promote phenotypic change of microglia from “classically” M1 activated to “alternatively activated” M2 states and enhances hematoma clearance, thereby reducing hydrocephalus by activation of PPARγ via AdipoR1 signaling." (PMID 35720361, 2022). "AdipoR1-mediated activation of the APPL1/LKB1/AMPK/PPARγ pathway had a critical role in the M1 to M2 transformation, as well as in the process of hematoma resolution." (PMID 35720361, 2022). "In vivo test, activation of PPARγ can accelerate the clearance of hematoma, reduce brain edema, and promote recovery nerve function." (PMID 35517804, 2022). "For example, monascin, which participates in the dual activation of PPARγ and Nrf2, has been shown to improve long-term outcomes by facilitating hematoma clearance." (PMID 36245922, 2022). "Statins enhance hematoma clearance and improved neurological outcome in a PPARγ-dependent manner in a rat ICH model." (PMID 33206327, 2021). "Simply put, THCQ-H can stimulate phagocytosis through PPARγ and promote the regression and elimination of hematomas, which can reduce inflammation and toxicity and upregulate cellular defense mechanisms." (PMID 34012394, 2021). "Preclinical and experimental studies have shown that PPARγ activators are capable of promoting endogenous hematoma clearance." (PMID 31939088, 2020). "CD36 expression is regulated by peroxisome proliferator-activated receptor γ (PPARγ), and activation of PPARγ has been shown to promote hematoma resolution and decrease neuronal damage following ICH." (PMID 32695110, 2020). "In macrophages, PPARγ may act as an important factor in promoting hematoma absorption and protecting other brain cells from ICH-induced damage." (PMID 26021445, 2015). "Furthermore, PPARγ could stimulate hematoma regression mediated by phagocytosis, and facilitate the cleanup of the hematomas, which may reduce the generation of inflammation and toxicity." (PMID 30618863, 2018). "Activation of PPARγ or Nrf2enhances CD36 expression and erythrophagocytosis of microglia/macrophages,thereby promoting hematoma resolution and neurological recovery after ICH." (PMID 41504200, 2025). "Flores and his colleagues confirmed that PPARγ agonists (15d-PGJ2) raised short-term PPARγ levels, accompanied with enhanced CD36 expression and accelerated hematoma resolution." (PMID 30618863, 2018). "Furthermore, PPARγ is known to regulate CD36 and CD163 expression, which allows participation in hematoma clearance after ICH." (PMID 36245922, 2022).
Infertility (15 papers, 2005 to 2025). "Similarly, DMRT1 loss of function has been demonstrated in infertile men while PPARG plays a role in testis fatty acid dysmetabolism in men with impaired spermatogenesis." (PMID 40086448, 2025). "Support from a larger study will inform the clinical use of PPARγ modulators—especially a physiological inhibitor of PPARγ, cPA—which have the potential to treat infertility originating from poor ovarian reserves." (PMID 32354153, 2020). "A significant positive correlation between BPA serum levels and the expression of all NRs but PPARγ, was observed in infertile subjects, consistently with previous observations in women." (PMID 26445054, 2015). "Infertile women from the metropolitan area displayed significantly higher levels of: BPA compared to fertile women (14.9 vs. 0.5 ng/mL serum); BPA and MEHP compared to infertile women from urban and rural areas; enhanced expression levels of NRs, except PPARγ." (PMID 25268510, 2014). "Infertile women from the metropolitan area displayed significantly higher expression levels of all NRs, but PPARγ, when compared to infertile women from the other two areas (p < 0.01 for both comparisons." (PMID 25268510, 2014). "As the relationship between PPARγ and infertility is controversial, we decided to organize this study aiming to examine correlation between PPARγ protein level in granulosa cells and pregnancy rate in women undergoing in-vitro fertilization (IVF) treatment." (PMID 25242989, 2012). "The ability of PPARγ to regulate ovarian function has been illustrated by agonists regulating steroid production by ovarian cells in vitro, and the sub- or infertility observed in animals with PPARγ disrupted in the ovary." (PMID 16131403, 2005). "It is known that untreated hypothyroidism may result in several health problems, including infertility and, in this case, PPARγ inhibition contributed to testicular damage, exacerbating OS and inflammation." (PMID 40001905, 2025). "Further research is needed to understand the complex molecular mechanisms behind the role of PPARγ in endometrial physiology, which may lead to new therapeutic options for infertility but also in the process of assisted reproduction." (PMID 38994935, 2024). "Additionally, it offers fresh perspectives on the Nrf2/PPARγ pathway concerning endometrial receptivity and its potential implications for infertility." (PMID 38994935, 2024). "Investigating the influence of PPARγ on oocyte and follicular cell growth and maturation is also needed due to its high expression in granulosa cells of developing follicles and the sub- and infertility observed in mice with PPARγ disrupted in the ovary." (PMID 16131403, 2005). "On the other hand, while a significant negative correlation between PFOA and all NRs included in the panel, with the exception of PPARγ, was found in infertile men, in infertile women such negative correlation was observed only with AhR." (PMID 26445054, 2015). "Because the expression of PPARγ was not disrupted in the uterus of these transgenic females, the lesion responsible for the sub- and infertility most likely lies within the ovary." (PMID 16131403, 2005).